GNA11 (G protein subunit alpha 11)
Diseases named in the same sentence as GNA11 in open-access papers (continued):
Sharing a sentence is not in itself a finding about the gene and the disease.
uveal melanoma (continued). "Uveal melanoma (UM) has well-characterised somatic copy number alterations (SCNA) in chromosomes 1, 3, 6 and 8, in addition to mutations in GNAQ, GNA11, CYSLTR2, PLCB4, BAP1, SF3B1 and EIF1AX, most being linked to metastatic-risk." (PMID 32340176, 2020). "A phase II study with selumetinib (an ATP-independent inhibitor of mitogen-activated protein kinase) showed improved clinical activity compared with temozolomide in GNAQ/GNA11 mutant uveal melanoma." (PMID 31320990, 2019). "In this report, we demonstrate that Tris DBA palladium is effective in vitro against a panel of human uveal melanoma cell lines with mutations in GNAQ and GNA11." (PMID 31320995, 2019). "Of 63 Chinese samples with uveal melanoma, we found seven somatic Q209 mutations in GNAQ (11.1%) and 14 Q209 mutations in GNA11 (22.2%)." (PMID 35693877, 2019). "Among Uveal Melanoma (UM) driver mutations, those involving GNAQ or GNA11 genes are the most frequent, while a minor fraction of tumors bears mutations in the PLCB4 or CYSLTR2 genes." (PMID 31216772, 2019). "We sequenced and explored the most frequent mutations and novel missense somatic mutations in the entire coding regions of exons 4 and 5 in GNAQ and GNA11 in Chinese uveal melanoma samples." (PMID 35693877, 2019). "Genes that were known to be mutated in cutaneous and uveal melanoma subtypes, including BRAF, NRAS, NF1, GNAQ and GNA11, were rarely mutated in our cohort of patients." (PMID 30847022, 2019). "Activating Q209L/P mutations in GNAQ or GNA11 (GNAQ/11) are present in approximately 5.6% of tumors and 80% of uveal melanomas." (PMID 31320990, 2019). "Combination of small molecules inhibiting MEK and PI3K enhances uveal melanoma cell death in a mutant GNAQ/GNA11-dependent manner." (PMID 31320990, 2019). "In uveal melanoma (UVM) cohort, 2.54% were recurrent GNA11 (p.Q209P) mutations, 2.01% were recurrent GNAQ p.Q209P, and 0.75% GNAQ p.Q1209L." (PMID 30890735, 2019). "Recurrent activating somatic mutation in GNA11 or GNAQ (NM_002067.2: c.626A > T, p.Q209L or NM_002072.3: c.626A > C, p.Q209P, respectively), a typical molecular sign of uveal melanoma, have been detected in all five cases." (PMID 29769598, 2018). "Transcriptomic studies identified distinct mutations including somatic mutations in GNAQ and GNA11, detected in more than 80%, and contribute to the upregulation of the mitogen-activated protein kinase (MAPK) pathway and the development of uveal melanoma (UM)." (PMID 29850322, 2018). "GNA11 encodes a q subunit of a GTP binding protein and is mutated in uveal melanoma; (d) subtype 4 is characterized by abnormalities of the RAS gene encoding a small GTPase." (PMID 29156643, 2017). "The conclusion of these studies was that more than 80% of uveal melanomas had somatic mutations in GNAQ or GNA11, implying that MAPK activation is a major contributor to the development of uveal melanoma." (PMID 29156643, 2017). "Uveal melanomas, in contrast to conjunctival melanomas, lack BRAF or NRAS mutations but frequently have mutations in GNAQ, GNA11, BAP1, SF3B1 or EIF1AX." (PMID 28938534, 2017). "By this means it genetically resembles human uveal melanomas, as about 80% of patients carry a G-protein (GNAQ and/or GNA11) mutation as an early event in tumorigenesis." (PMID 27366747, 2016). "Oncogenic resemblance with human uveal melanoma is given as uveal tumorigenesis is driven by an inserted plasmid with a mitfa:GNA11 Q209L overexpression (Rose, unpublished data)." (PMID 27366747, 2016). "Like uveal melanomas, primary leptomeningeal melanocytic neoplasms (LMNs) frequently carry GNAQ and GNA11 mutations." (PMID 26769193, 2016). "With respect to the signaling pathways altered in these tumors, mutations in GNAQ and GNA11 appear to activate the RAS pathway in MABN, uveal melanoma and other melanocytic lesions." (PMID 27057633, 2016). "Uveal melanoma is characterised by mutations in GNAQ and GNA11, resulting in Ras/Raf/MEK/ERK pathway activation." (PMID 26059332, 2015).
uveal melanoma (continued). "The landmark studies on the association of uveal melanoma with GNAQ and GNA11 mutations were conducted in Caucasian populations while the status of GNAQ and GNA11 mutations in uveal melanomas of Chinese has not been investigated yet." (PMID 25280020, 2014). "GNAQ and GNA11 mutations, which are potential drivers of MAPK activation, have been reported in blue nevi and in up to 85% of cases of uveal melanoma." (PMID 25030020, 2014). "Uveal melanoma most frequently carry mutations in the GNAQ, GNA11, and BAP1 genes, where GNAQ/GNA11 mutations are mutually exclusive." (PMID 25106493, 2014). "These mutations remained undetected in uveal melanomas until recently GNAQ and GNA11 mutations in uveal melanoma were identified." (PMID 25280020, 2014). "Mutant alleles of the GNA11 or GNAQ genes, which are highly specific for uveal melanoma, were identified in cfDNA of 9 of 22 (41%) patients." (PMID 23634288, 2013). "In contrast, genetic alterations in uveal melanoma such as GNAQ and GNA11 mutations were also found in selected cases of cutaneous melanoma and are frequently found in blue nevi (benign cutaneous melanocytic tumors)." (PMID 23694694, 2013). "In uveal melanoma a different set of genes shows recurrent mutations, including GNAQ and GNA11, with activating mutations as well as in BAP1 showing inactivating mutations." (PMID 23694694, 2013). "Particularly frequent somatic mutations of the GNA11 gene at codon 209 in exon 5 and codon 183 in exon 4, resulting in mutant GNA11Q209L and GNA11R183C, respectively, have been reported in uveal melanoma and blue nevi." (PMID 24137342, 2013). "It had long been noted that uveal melanomas have constitutive MAPK signaling, and it is now understood that it is because of the presence of GNAQ or GNA11 mutations." (PMID 22515704, 2012). "BRAF and NRAS mutations are absent in melanomas arising in the uveal layer of the eye, but mutually exclusive somatic mutations in the heterotrimeric G protein alpha-subunit, GNAQ, or in GNA11, are present in the great majority of uveal melanomas." (PMID 22515704, 2012). "Mutually exclusive mutations in G Protein Subunit Alpha Q (GNAQ) and G Protein Subunit Alpha 11 (GNA11), members of the Gαq family of proteins, frequently initiate neoplastic proliferation of uveal melanocytes, serving as a primary driver in uveal melanoma pathogenesis." (PMID 41160198, 2025). "Despite the rarity of this tumor type, several seminal articles have highlighted that approximately 80–90% of uveal melanomas possess a GNAQ or GNA11 mutations but it does not have a clear relationship with overall survival in patients with UM." (PMID 40000790, 2025). "In one vfDNA+/UM− patient, the primary uveal melanoma was known to carry two clonally-abundant Gαq signalling mutations (GNA11 p.R183H and PLCB4 p.D630N in vfDNA-29), but the vfDNA only contained wild-type GNA11 and PLCB4 in comparable concentrations." (PMID 40240901, 2025). "Given that PAK inhibition sensitizes mutant RAS- and BRAF-driven cell lines to the inhibition of the MAPK cascade, we hypothesized that PAK inhibition would also be able to sensitize GNAQ and GNA11 mutant uveal melanoma cells to MEK inhibitors." (PMID 41154654, 2025). "Uveal melanoma (UM) is an aggressive cancer emerging from mutations in the GNAQ and GNA11 genes." (PMID 39518110, 2024). "Furthermore, sequencing of exon 4 of both GNA11 and GNAQ genes, affecting codon R183 (arginine 183), showed a lower prevalence of mutations: 4.9% of primary uveal melanomas and 2.1% of blue nevi." (PMID 39518110, 2024). "GNAQ and GNA11 mutations were common in uveal melanomas, while MAP-Kinase mutations were frequent in non-uveal melanomas with NF1, BRAF V600 and NRAS Q61 mutations occurring in decreasing frequency, consistent with a strong UV association." (PMID 38903495, 2024). "The GNA11 mutation, like the GNAQ mutation, is also implicated in uveal melanoma in adults." (PMID 39598668, 2024).
uveal melanoma (continued). "According to preliminary research, uveal melanoma with mutations in GNAQ and GNA11 is responsive to MEK inhibitors and could be used as a model for medical treatment for CH." (PMID 37106420, 2023). "ctDNA in non-cutaneous melanoma—In uveal melanoma (UM), recurrent mutations affecting GNA11, GNAQ, PLCβ4 or CYSLTR2 are found in the majority of patients and, even if they are not determinants of prognosis, they can represent targetable mutations in the blood." (PMID 38201222, 2023). "Similarly, a MEK inhibitor failed to significantly improve the overall survival in GNAQ- and GNA11-driven uveal melanoma, either when used alone or added to conventional chemotherapy." (PMID 37830586, 2023). "For example, GTF2I is specific to thymomas, whereas GNAQ and GNA11 are specific to uveal melanomas." (PMID 35975235, 2022). "In particular, hot spot mutations in GNAQ and GNA11, referred to as GNAQ oncogenes, encoding GTPase-deficient and constitutively active Gαq proteins, have been identified in ∼93% of uveal melanoma (UM) and 4% of skin cutaneous melanoma, where they act as driver oncogenes." (PMID 36596361, 2022). "A total of 99 of these 118 patients (84%) had detectable ctDNA at baseline and on treatment, of whom 94 had mutations detected in one or more uveal melanoma genes (GNAQ, GNA11, SF3B1, PLCB4, CYSLTR2) at a variant allelic frequency of >0.3 at baseline and were included in the analyses." (PMID 36229663, 2022). "Uveal melanomas generally harbor early initiating mutations in genes encoding for the G-α-protein-subunits, GNAQ or GNA11, with the remainder of cases harboring other alterations, such as mutations in CYSLTR2 or PLCB4, which functionally activate the G-α pathway." (PMID 34771668, 2021). "Uveal melanoma is frequently associated with mutations in the CYSLTR2, PLCB4 and GNAQ/GNA11 genes." (PMID 34359771, 2021). "Nevertheless, these data do not explain the GNAQ/GNA11 selective mutational pressure observed in uveal melanoma compared to cutaneous melanoma or why they are considered to be oncogenic." (PMID 32532044, 2020). "Furthermore, as a consequence of GNAQ/GNA11 mutation, an upregulation of MET has been implicated in uveal melanoma." (PMID 31109147, 2019). "Since primary uveal melanoma tumours and liver metastases, characterised by mutations in GNAQ or GNA11, have constitutive activation MAPK signalling via alternative, similar therapies targeting downstream effectors of the MEK pathway, Akt and protein kinase C (PKC) were recently investigated." (PMID 31109147, 2019). "The results showed that 33% of Chinese uveal melanoma samples carried Q209 mutations while none had R183 mutation in GNAQ or GNA11." (PMID 35693877, 2019). "Several tumors, including uveal melanoma, show somatic mutations of GNAQ/GNA11." (PMID 31336681, 2019). "No somatic mutations in R183 in exons 4 of GNAQ and GNA11 were found in 63 Chinese uveal melanoma samples." (PMID 35693877, 2019). "Interestingly, in a subsequent study in uveal melanoma, mutations in GNAQ and GNA11 were found to promote YAP/TAZ activity." (PMID 29642615, 2018). "In this study, we examined interferon-γ (IFNγ) responses in a large panel of immune checkpoint inhibitor-naïve melanoma cells with defined genetic drivers; BRAF-mutant (n = 11), NRAS-mutant (n = 10), BRAF/NRAS wild type (n = 10), and GNAQ/GNA11-mutant uveal melanomas (UVMs) (n = 8)." (PMID 29977240, 2018). "Like cutaneous melanoma, CM frequently harbors a BRAF mutation, as opposed to GNAQ/GNA11 mutations which are found in most cases of uveal melanoma." (PMID 28938534, 2017). "Another recent study reported the recurrent mutation in PLCB4, occurring in about 4% of uveal melanomas; importantly, PLCB4D630Y mutations are mutually exclusive with mutations in GNA11 and GNAQ, in line with the observation that PLCB4 is a canonical downstream target of GNA genes." (PMID 29156643, 2017).
uveal melanoma (continued). "The second point is that uveal melanoma patients without GNAQ or GNA11 mutations tend to have a worse prognosis than those with GNAQ or GNA11 mutations." (PMID 27148356, 2016). "Importantly, 80–96 % of uveal melanomas harbour mutations in either the guanidine nucleotide binding protein (G protein), Q polypeptide 1 (GNAQ) or the G protein alpha 11 (GNA11) gene, in a mutually exclusive pattern." (PMID 26059332, 2015). "The most significant single chromosomal marker of poor outcome in uveal melanoma is loss of one copy of chromosome 3, while activating mutations in the alpha subunit of heterotrimeric G proteins, GNAQ or GNA11, are considered an early event in the development of the disease." (PMID 25166211, 2014). "Considering that about 80% of primary tumors or uveal melanoma metastases show mutant GNA11 or GNAQ genes 18, it is plausible that only a few of the remaining 13 patients had tumors without one of these mutations, and therefore, were uninformative for our study." (PMID 23634288, 2013). "This would be in line with the greater role of GNA11 in advanced stages of uveal melanoma." (PMID 23634288, 2013). "We hypothesized that an increased melanoma risk in familial melanoma families with uveal melanoma and/or blue nevi is due to GNAQ and GNA11 germ-line mutations in exon 5 which result in constitutive activation of the MAPK pathway." (PMID 23825798, 2013). "In summary, we report the absence of germ-line mutations in exon 5 of GNAQ and GNA11 in familial melanoma pedigrees with an increased incidence of uveal melanoma and/or blue nevi." (PMID 23825798, 2013). "To establish a reliable, noninvasive assay that might allow early detection and monitoring of metastatic disease, we determined the proportion of GNAQ or GNA11 mutant reads in cfDNA of uveal melanoma patients by ultradeep sequencing." (PMID 23634288, 2013). "GNA11 mutations were analyzed in all types of thyroid cancer (PTC, FTC and ATC) as they have been frequently identified in uveal melanoma and are known to activate the MAPK signaling pathway, which is one of the most deregulated signaling pathways in thyroid cancer." (PMID 24137342, 2013). "Although the MAP-kinase cascade is a mutational target in several tumor entities, activation of this pathway by mutations in either GNAQ or GNA11 is specific for uveal melanomas and other nonepidermic melanocytic lesions like blue nevi 19,20,21." (PMID 23634288, 2013). "Interestingly, uveal melanomas, or melanomas which originate from the choroid, as well as diffuse melanocytic CNS lesions, such as neurocutaneous melanosis and blue nevus melanoma/nevus of Ota also frequently exhibit GNAQ and GNA11 mutations." (PMID 41303082, 2025). "Therefore, we set forth to investigate whether GNAQ/GNA11-driven uveal melanoma cells also exhibit heightened sensitivity to PAK inhibition." (PMID 41154654, 2025). "Additionally, non-uveal melanomas with GNAQ/GNA11 mutations tend to metastasize lymphatically, similar to cutaneous melanoma, rather than the hematogenous metastasis typically seen in uveal melanoma." (PMID 38474231, 2024). "Furthermore, reflex testing for GNAQ and GNA11 is recommended for all uveal melanomas in Ontario." (PMID 39661469, 2024). "In the article, we attempt to comprise knowledge available from clinical trials and meta-analyses and assess whether there is any correlation between the occurrence of benign skin blue nevi or hemangiomas with uveal melanoma and other medical conditions caused by GNAQ and GNA11 mutations." (PMID 39518110, 2024). "Expansion into publicly available bulk and single cell uveal melanoma sequencing data allowed to evaluate our findings in independent cohorts of primary and metastatic tumours and to study the role of wild-type CYSLTR2 in melanomas with a mutation in GNAQ, GNA11 or PLCB4." (PMID 33588787, 2021).
uveal melanoma (continued). "Interestingly, uveal melanoma driver mutations in GNAQ/GNA11 were identified for a decade, but their discovery did not lead to mutation-specific drug development, unlike it the case for BRAF mutations in cutaneous melanoma which saw enormous success." (PMID 32532044, 2020). "Thus, GNAQ, GNA11, PLCB4, and CYSLTR2 form four modules of independent mutated uveal melanomas." (PMID 29156643, 2017). "In addition, it would be very interesting to correlate tumor progression with both EDNRB expression and the presence or absence of GNAQ and GNA11 mutations in uveal melanoma." (PMID 27148356, 2016). "However, recently, novel established permanent cell lines from primary and metastatic uveal melanomas exhibiting a characteristic genetic profile (including GNAQ, GNA11, or BAP1 mutations) allow for further investigations on genetic pathways and their influence on tumor progression and metastasis." (PMID 27366747, 2016). "Oncogenic mutations in GNAQ and GNA11 result in constitutive activation of these proteins and downstream signalling of pathways such as the YAP pathway, the phosphoinositide-3 kinase/AKT and the Ras/Raf/MEK/ERK pathway, thus playing a key role in the development and progression of uveal melanomas." (PMID 26059332, 2015). "No mutations were found in GNA11 in this small set of uveal melanomas." (PMID 22536370, 2012). "Responses were seen in tumours harbouring BRAF fusions, GNA11, GNAQ, KRAS, NF1, and NRAS alterations, most frequently in low-grade serous ovarian cancer, central nervous system tumours, and uveal melanoma." (PMID 41664938, 2026). "To this end, we treated uveal melanoma cell lines 92.1 (GNAQ mutant), Mel202 (GNAQ mutant), and MP41 (GNA11 mutant) with a range of doses of IPA3 and PF3758309." (PMID 41154654, 2025). "Genetics and immunology will be cutting-edge research areas in uveal melanoma, with attention to genes such as GNAQ, GNA11, and BAP1, highlighted as important focus points." (PMID 39898362, 2025). "A cyclic depsipeptide, FR90059, that directly interacts with GNA11, preferentially inhibits downstream ERK1/2 signaling and thereby has anti-proliferative and pro-apoptotic effects on uveal melanoma cell proliferation." (PMID 36313756, 2022). "A recent study suggested that combining the HDI entinostat with dual human epidermal growth factor 2 and the epidermal growth factor receptor neratininb leads to internalization and degradation of mutant GNA11 and GNAQ in uveal melanoma models." (PMID 34533562, 2021). "Furthermore, only one subclonal variant of unknown significance in GNAQ and no GNA11 mutations, usually present in uveal melanoma, were found." (PMID 31500314, 2019). "A panel of human uveal melanoma cell lines, including mutants in GNAQ, GNA11, and wild type were treated with a dose range of Tris DBA palladium, and cell number was evaluated at 24 hours." (PMID 31320995, 2019). "Analysis of the GNA11 and GNAQ genes in two metastatic uveal melanomas revealed GNA11 p.Q209L and GNAQ p.Q209P, respectively." (PMID 31277584, 2019). "We extracted somatic DNA from paraffin-embedded biopsies of 63 Chinese uveal melanoma samples and sequenced the entire coding regions of exons 4 and 5 in GNAQ and GNA11." (PMID 35693877, 2019). "Gene mutations in cutaneous melanoma (BRAF, N-Ras, etc.)were entirely different from those in uveal melanoma (GNAQ, GNA11, etc.)." (PMID 25184134, 2014). "The lack of GNAQ and GNA11 germ-line mutations in familial melanoma pedigrees with an increased incidence of uveal melanoma and blue nevi further is supportive of the importance of sporadic mutations in these genes in blue nevi and uveal melanoma as previously published." (PMID 23825798, 2013). "Uveal melanoma (UM) cells are characterized by the presence/absence of BAP1 protein and mutation in the GNAQ/GNA11 genes." (PMID 39195238, 2024).